CSF1 (colony stimulating factor 1)
Diseases named in the same sentence as CSF1 in open-access papers (continued):
Sharing a sentence is not in itself a finding about the gene and the disease.
tumor (continued). "In a mouse model of BrC, Swierczak and colleagues found that blocking the CSF-1 (M-CSF)/CSF-1R interaction to prevent recruitment of circulating monocytes and M2 polarization increased the serum levels of G-CSF, leading to increased neutrophils in the primary tumor, and increased lung metastasis." (PMID 28337194, 2017). "Furthermore, anti-CSF-1/CSF-1R therapies have produced encouraging therapeutic responses in pre-clinical tumour models, particularly in combination with chemotherapy or radiotherapy, or when used to reprogram tumor-promoting TAMs into anti-tumoral TAMs." (PMID 28629162, 2017). "Indeed, tumor cells produce CSF-1, which induces migration of macrophages." (PMID 28471401, 2017). "Moreover, autophagy provides pro-survival signals to protect myeloid cells from stressful tumor microenvironments, and bestows the surviving tumor-infiltrating myeloid cells with the ability to gain pro-tumorigenic properties through tumor-derived factors such as CSF-1." (PMID 28686632, 2017). "Given that CSF-1 is increased by cisplatin treatment, and that the CSF-1Rpos cells are chemoresistant, important to evaluate which signals modulate the expression of CSF-1 and CSF-1R within the context of a stress induced tumor rearrangement and whether the CSF-1R ligand may work as a SASP cytokine." (PMID 27486763, 2016). "Therefore, we concluded that Tm4sf1 and Csf1 found to be overexpressed in lung TCs may have a role in tumour promotion." (PMID 25278030, 2014). "Thus, an alternative mechanism must exist leading to CSF1 upregulation in this tumor subset." (PMID 24604026, 2014). "Furthermore, CSF1 secretion can affect the microenvironment of the tumor." (PMID 25313137, 2014). "Furthermore tumor cell hypoxia is known to regulate CSF-1 expression." (PMID 25051364, 2014). "In contrast, CSF-1 deficiency did not affect development or growth of the primary tumour." (PMID 22005011, 2011). "The CSF1 translocation was identifiable in only three out of the eight case specimens recruited in this study, a finding not unexpected considering that the CSF1 translocation can only be detected in about 60% of cases and even then in only a small minority of tumor cells (about 2%)." (PMID 20981142, 2010). "Thus, aberrant CSF1 signaling plays a critical role in tumor development and progression in PVNS/TGCT, which may therefore represent the ideal index disease to test the therapeutic value of CSF1 inhibitors." (PMID 20981142, 2010). "Thus, we hypothesize that the selective localization of RAW 264.7 macrophages to the tumor periphery occurs in response to a CSF-1 gradient generated between hypoxic and the normoxic regions of the tumor." (PMID 19696929, 2009). "Consistent with our Visium analysis, Xenium gene expression analysis revealed that Tfh-like cells located near tumor regions were enriched for C06b CD103+ Tfh-like signature genes, including CCL5, CCL4, GZMA, HAVCR2, and CSF1." (PMID 41542042, 2026). "Conversely, M2 phenotype macrophages, induced by TGF-β, IL-4, IL-10, IL-13, colony-stimulating factor-1 (CSF-1), and C-C motif chemokine ligand 2 (CCL2), exert anti-inflammatory and tumor-supportive effects." (PMID 41590379, 2026). "A well-known positive feedback loop is the Endothelial Growth Factor–Colony Stimulating Factor-1 (EGF-CSF-1) circuit: Tumor cells release CSF-1 to recruit and differentiate macrophages, while TAMs secrete EGF, which enhances tumor cell migration and invasion." (PMID 41597210, 2026). "Studies have shown that blockade of the CSF1/CSF1R pathway reduces the number of M2 TAMs and decreases PD‐L1 and ARG1 expression; it also reshapes the tumor immune microenvironment and enhances sensitivity to immune checkpoint inhibitor therapy." (PMID 41426206, 2026). "Colony stimulating factor 1 (CSF1) receptor inhibitors have proven effective at symptom palliation and reducing tumor burden in approximately 40% of patients." (PMID 41523664, 2026).
tumor (continued). "M2 TAMs activate the CSF1/CSF1R axis in response to signals such as heat shock protein (HSP)90α secreted by CAFs and tumor cells." (PMID 41426206, 2026). "Blocking the CSF1/CSF1R axis reduces M2-like TAMs infiltration and tumor metastasis, offering a promising strategy for metastatic CRC." (PMID 41639044, 2026). "Hypoxic tumor cells secrete chemotactic factors like VEGF, CCL2, CSF-1, and endothelins to attract monocytes/macrophages into oxygen-deprived regions." (PMID 41597210, 2026). "They activate the CSF1/CSF1R and IL‐10/STAT3 pathways, induce T‐cell exhaustion and metastatic phenotype switching, promote tumor infiltration and metastasis, and substantially shorten disease‐free and overall survival." (PMID 41426206, 2026). "We stained two sequential tumor sections – one using IHC for TMEM doorways (Iba1, Endomucin, Mena) and the second using IF for CSF-1, dextran, and endothelial cells (endomucin) and aligned the images of stained sections to the single cell level." (PMID 40646332, 2025). "The molecular pathogenesis of TGCT involves genomic alterations at the colony-stimulating factor 1 (CSF1) locus (1p13), resulting in aberrant CSF1 overexpression in a subset of tumor cells." (PMID 40900794, 2025). "has shown enhancement of non‐irradiated tumor regression and increased CD8+ T cells infiltration after combining radiotherapy with depleting recruited macrophages by anti‐CSF‐1 antibodies." (PMID 40400098, 2025). "Previous studies have implicated signaling pathways and cytokines such as CCL8, CCL2/CCR2, CSF-1/CSF-1R, STAT3, STAT6, MMPs, AMPK, TLR3, and SIRPα in the regulation of TAMs and tumor progression." (PMID 39781471, 2025). "To ascertain the role of tumor cell-secreted CSF-1 in stimulating macrophage VEGF-A secretion, we used the same co-culture system of MDA-MB-231 tumor cells and BAC1.2F5 macrophages as above." (PMID 40646332, 2025). "This study evaluated the clinical significance of the proportion of the hepatoid component within the tumor, CD163 + macrophages, and macrophage colony-stimulating factor-1 (CSF-1) in HAS." (PMID 39488822, 2025). "scRNA-seq showed that the CSF-1R ligands (CSF-1 and IL34) as well as CSF-1R were primarily expressed in tumor cells and TAMs, with the highest expression of IL34/CSF-1 in GBM cells and the highest expression of CSF-1R in microglia." (PMID 41365876, 2025). "Peripheral monocytes are recruited to the Br-TME and differentiate into TAMs by factors such as CCL2, CCL18, CCL20, CSF1, and the vascular endothelial growth factor (VEGF), which are derived from both tumor cells and stromal cells." (PMID 40649751, 2025). "These signaling events create a chemotactic axis in which the CSF-1/EGF signals become amplified, allowing the tumor cells and macrophages to remain in close proximity with each other as they migrate together as cell pairs (a process called streaming)." (PMID 40646332, 2025). "In summary, we show that CSF-1, TLR4, and Th2 pathways collectively prepare myeloid–lymphatic progenitors to fuse with tumor LECs, leading to increased proliferation, lymphatic density, and LN metastasis." (PMID 40507286, 2025). "CSF-1 binds to CSF1R receptors which are highly expressed on the surface of macrophages and biases their movement towards the tumor." (PMID 40464993, 2025). "The tumor cells respond to EGF-secreting macrophages by migrating towards them and secreting more CSF-1, therefore generating a paracrine loop." (PMID 40646332, 2025). "We found that knockdown of AXL significantly reduced the expression of CCL-2, CSF-1, IL-10, and TGF-β cytokines in ccRCC tumor cells." (PMID 41029360, 2025). "Emactuzumab, another monoclonal antibody against CSF1, enhances anti-tumor immune responses by decreasing the number of F4/80+ TAMs within tumors and increasing the CD8+/CD4+ T cell ratio through inhibition of the CSF1/CSF1R-signaling pathway." (PMID 41019045, 2025).
tumor (continued). "Nearly all these proteins were detected in CSF-1 primed myeloid precursors activated by TLR4 or Th2 ligands in vitro and in tumor-recruited M-LECPs in vivo." (PMID 40507286, 2025). "Cytokines and chemokines secreted by tumor cells, such as IL10, CCL2, and CSF1, are key drivers of TAM plasticity within the pro-tumor microenvironment." (PMID 40730813, 2025). "Tumor cells secrete chemokines like CCL2, CCL5, and CSF-1 that recruit monocytes from the bloodstream into the TME, where they differentiate into TAMs." (PMID 39930476, 2025). "CAFs recruit MDSCs from the bone marrow to the tumor site by secreting cytokines such as CCL2, CSF-1 and IL-6." (PMID 40934009, 2025). "This paracrine loop, mediated by tumor cell-secreted CSF-1 and macrophage-secreted EGF, is critical in facilitating the co-migration of tumor cells and macrophages toward blood vessels." (PMID 40547026, 2025). "As in the CSF-1R blocking antibody experiments, blocking tumor-derived CSF-1 inhibited TMEM doorway activity, increased vascular integrity, and decreased dissemination of tumor cells as CTCs." (PMID 40646332, 2025). "However, since CSF1, a known target of the Hh pathway, can induce F4/80 expression in macrophages, we cannot exclude the possibility that the reduction in F4/80‐positive cells observed in GLI1 KO PLC5 tumour may be partially due to downregulation of CSF1 expression." (PMID 40913253, 2025). "MCS110, a humanized monoclonal antibody that binds CSF1 and blocks downstream signaling, was administered as monotherapy in TGCT and reduced tumor size." (PMID 41417432, 2025). "Tumor-associated macrophages (TAMs), derived from circulating monocytes recruited to tumor sites via chemotactic signals such as C-C motif ligand 2 (CCL2) and colony-stimulating factor-1 (CSF-1), are pivotal components of the tumor microenvironment (TME)." (PMID 40850976, 2025). "Tumor cells secrete a wide array of cytokines and chemokines such as CCL2, CSF-1 (M-CSF), IL-6, IL-10, and TGF-β that directly polarize macrophages." (PMID 41425545, 2025). "CCL8 recruits monocytes, induces CSF-1 production to maintain TAM survival and proliferation, and binds SIGLEC1 to enhance tumor cell motility; inhibition of the CSF-1/CSF-1 receptor axis reduces angiogenesis." (PMID 40869364, 2025). "This interaction is driven by a CSF-1/EGF paracrine loop, wherein tumor cells secrete CSF-1 (which attracts CSF-1R-expressing macrophages), while macrophages in turn secrete EGF (which attracts EGFR-expressing tumor cells)." (PMID 40646332, 2025). "During tumor development, inflammatory signals recruit macrophages to the tumor stroma, including chemokines (e.g., CCL2, CCL5, CXCL12), cytokines (e.g., VEGF, CSF1), and complement factors." (PMID 40872551, 2025). "Crosstalk with tumor cells through exosomes and soluble factors (e.g., CCL2, CSF-1) reprograms TAMs toward pro-tumor phenotypes." (PMID 40422244, 2025). "During tumorigenesis, inflammatory monocytes from the peripheral blood are attracted to the tumor site by chemokines such as CCL2, as well as cytokines including CSF-1 and VEGF." (PMID 41058699, 2025). "Simultaneously, differentiation- and immune-activating signals such as CSF1, TNFSF9, KITLG, EHF, and CHRM1 were downregulated, potentially modulating tumor immune escape and proliferation in a context-dependent manner." (PMID 41009714, 2025). "Meanwhile, TAM membranes absorb colony-stimulating factor 1 (CSF1) via increased expression of its receptor (CSF1R) on TAM membranes, reducing TAMs in tumor tissues and relieving TIM." (PMID 40225567, 2025). "In murine BC models, the inhibition of CSF1/CSF1R signaling through either CSF1 monoclonal antibodies or the CSF1R tyrosine kinase inhibitor PLX3397 results in the depletion of TAMs and significantly postpones tumor recurrence following radiotherapy." (PMID 40092996, 2025).
tumor (continued). "CSF1 is well-known as a cytokine that modulates macrophages, which play an active role in the GBM TME and can promote tumor development through differentiation toward the M2 phenotype." (PMID 40287444, 2025). "In B-lymphoma cells and murine models, the muting of CREBBP/EP300 in tumor cells resulted in polarization of TAMs towards the M2 phenotype by activating the NOTCH signaling pathway and downstream CCL2/CSF1 axis." (PMID 40216772, 2025). "Following RT, a range of immunosuppressive cytokines, such as CSF‐1, CCL2, and CXCL12, are released, which promote the recruitment of Treg cells, MDSCs, TAMs, and other immunosuppressive cells into the tumor tissue." (PMID 40900811, 2025). "M-MDSCs, along with monocytes, are predominantly drawn to the tumor by chemokines secreted by the tumor cells, including CCL2, CCL5, and CSF1." (PMID 40722739, 2025). "CSF-1 and TAMs are prominently present in the case of TNBC, contributing to tumor progression and creating an environment characterized by immunosuppression and pro-tumorigenic factors." (PMID 40297849, 2025). "Tumor cells secrete factors such as PDGF, CSF1, and VEGF that recruit macrophages to the tumor site." (PMID 41311372, 2025). "Using an ELISA on conditioned media, we confirmed that exogenous recombinant CSF-1 can stimulate macrophages to secrete VEGF-A and that tumor cells secrete CSF-1." (PMID 40646332, 2025). "For example, a series of drugs targeting CSF‐1/CSF‐R1 and CCL2/CCR2 signaling pathways have been developed to inhibit TAMs infiltration for anti‐tumor treatment." (PMID 40536254, 2025). "LAMs are myeloid-lineage cells derived from circulating monocytes, which are recruited into the LME by tumor, and EBV-derived factors such as CCL2, colony-stimulating factor 1 (CSF-1), and inflammatory cytokines." (PMID 41303704, 2025). "Functionally, xCT promotes PD-L1 and CSF1 expression through αKG-HIF1α cascade, resulting in intratumoral TA and MDSC infiltration and regulation of ferroptosis and the tumour microenvironment." (PMID 41154605, 2025). "An interesting study conducted on renal carcinoma cells demonstrated how tumor cells can influence the development of CD34+ progenitor cells into mature DCs through the production of IL-6 and CSF-1, which in turn bind to the CSF-1R." (PMID 39457693, 2024). "Given that tumor cells are the primary source of MCSF in the TME following RT, we depleted Csf1 of Lewis cells using short hairpin RNAs (shRNAs)." (PMID 39165639, 2024). "This process is mediated via a paracrine loop involving tumor-synthesized CSF1 and macrophage-produced EGF that drives the migration of tumor cells toward blood vessels." (PMID 39516356, 2024). "TAMs themselves are recruited to premetastatic niches by a variety of tumor-secreted factors, such as CCL2, CSF-1, VEGF, PDGF, TNF-α, and TGF-β, where they act in a similar manner as in primary tumors, promoting cancer cell survival." (PMID 39516356, 2024). "In response to this tissue damage, cells in the TME initiate a wound healing response by increasing their secretion of CSF1, CXCL12, and other chemokines that recruit these circulating progenitor cells to the tumor." (PMID 39555068, 2024). "The activation of the CSF-1R by its ligands, colony-stimulating factor 1 (CSF-1) and Interleukin-34 (IL-34), regulates TAM polarization towards an immunosuppressive M2 phenotype, promoting tumor progression and immune evasion." (PMID 39457693, 2024). "Anti-CSF-1 mAb, lacnotuzumab, was shown to enhance CD8+ T-cell tumor infiltration and sensitivity to paclitaxel in preclinical experiments and xenograft models." (PMID 38794298, 2024). "Targeting the CSF-1/CSF-1R axis has shown potential in reducing GAMM density and altering their phenotype towards a less tumor-supportive state." (PMID 39457693, 2024).
tumor (continued). "In vitro and in vivo migration assays and intravital imaging show that tumor cells and macrophages migrate through the TME together using a CSF1/EGF paracrine loop that leads to invasion and metastasis." (PMID 39555068, 2024). "In particular, CSF1 and/or PLK4 inhibition can increase the number of tumor-infiltrating M1 macrophages in GBM63,64, thereby reversing immunosuppression." (PMID 39054369, 2024). "The AS‐99 also reduced the H3K4me3 modification and expression of CSF1 and CCL2 in both tumor cells and HSCs." (PMID 39377228, 2024). "In HCC, SPP1 signals can crosstalk with the colony-stimulating factor-1 (CSF1) pathway to mediate the TME switch from Th1 to Th2, which is vital for tumor progression." (PMID 39616302, 2024). "First, TAMs secrete CSF‐1 in a paracrine manner to activate EGF signalling pathway in tumour cells, thereby inducing angiogenesis and distant metastasis of tumour cells." (PMID 38774995, 2024). "M2-TAMs are alternatively activated through IL-4, IL-10, IL-13, TGF-β, colony-stimulating factor 1 (CSF-1), or prostaglandin E2 (PGE2), and, differently than M1-TAMs, reveal immunosuppressive properties, promoting tumor growth, angiogenesis, and metastasis." (PMID 39408564, 2024). "For example, colony-stimulating factor 1 (CSF1) or CSF1 receptor (CSF1R) blockade has been shown to repolarize M2 to M1 macrophages and increase tumor sensitivity to other immunotherapies." (PMID 38612926, 2024). "The binding of CSF-1 to CSF-1R in macrophages can activate PI3K/AKT, Hippo, and Notch signaling pathways, which polarize macrophages to the pro-tumor M2 phenotype." (PMID 38474320, 2024). "Macrophages are recruited to tumor sites primarily through the CCL2/CCR2 axis and CSF-1/CSF-1R signaling, so blocking these two signaling axes also reduces macrophage infiltration." (PMID 38464516, 2024). "Similar to CCR5, many additional tumor-secreted factors, including VEGF and CSF-1, are also essential for macrophage recruitment." (PMID 39169402, 2024). "The majority of TAMs derive from circulating bone marrow (BM)-derived monocytes that migrate into the tumor bed mainly under the influence of chemokines (e.g. C-C motif ligand 2 (CCL2)), cytokine colony stimulating factor 1 (CSF-1), or complement components." (PMID 38426089, 2024). "Other pharmaceutical agents, including the CCL2 inhibitor bindarit, anti-CCL2 mAb carlumab, CSF1 inhibitor GW2580, and dequalinium-14, CD40 antagonist CP-870,893, have also shown anti-tumor effects by reducing macrophage infiltration." (PMID 39146202, 2024). "Cytokines and chemokines in TME, such as CSF1, GM-CSF, IL-1β, CCL2, and VEGF, can induce conformational changes in α4β1 integrins to promote myelopoiesis, monocyte-to-tumor trafficking, and infiltration by activating the corresponding signaling pathways." (PMID 38185636, 2024). "Factors secreted by tumor cells, such as MIC-1, CSF-1, TGF-β, and IL-33, impair the anti-tumor functions of microglia." (PMID 37307835, 2024). "RG7155 potently inhibited the viability of CSF-1-differentiated macrophages in vitro and reduced the number of CD68+ CD163+ TAMs in tumor biopsies from diffuse-type giant cell tumor patients." (PMID 39516356, 2024). "Chemokines such as CSF1 and CCL2, secreted by tumor cells, can recruit monocytes from peripheral blood to the TME, and then monocytes differentiate into macrophages." (PMID 38957393, 2024). "Sorafenib was reported to significantly increase the peripheral recruitment and intratumoral infiltration of macrophages in metastatic liver cancer, accompanied by an elevation of SDF-1α, CSF-1, and VEGF in the tumor stroma." (PMID 38787372, 2024). "A study found that the CSF1 modulation of TAM and tumor progression is affected by the transcription factor forkhead box protein O1 (FOXO1)." (PMID 39201328, 2024). "It is therefore worth noting that anti-inflammatory chemokines including CSF1, CD276, VEGFA, and CX3CL1 were upregulated in pedB tumor epithelial cells." (PMID 39482394, 2024).